MGMT (O-6-methylguanine-DNA methyltransferase)
Diseases named in the same sentence as MGMT in open-access papers (continued):
Sharing a sentence is not in itself a finding about the gene and the disease.
tumor (continued). "Although surface area of the tumor is rarely mentioned in the literature, one study suggested that location and shape of the tumor were less predictive of MGMT promoter methylation status, as compared to textural characteristics." (PMID 39531176, 2024). "The distribution of MGMT methylation and unmethylation frequencies demonstrated distinctive patterns across different tumor locations within the brain." (PMID 38893240, 2024). "The level of MGMT promoter methylation varies among tumor cells, and contamination by normal cells is common in all samples, impacting the results of real-time MS-qPCR." (PMID 40093343, 2024). "Classical prognostic factors include complete tumor resection, methylation of the MGMT (O6-MethylGuanine-DNA MethylTransferase) promoter, and the use of steroids." (PMID 38753169, 2024). "More recently, a DL pipeline has been utilised for automatic tumour segmentation and MGMT promotor status classification using T1w and T2-FLAIR images." (PMID 39009914, 2024). "Tumor specimens from the initial and recurrent tumor resection were subjected to evaluation of MGMT, p15, and p16 methylation statuses." (PMID 39335591, 2024). "At the univariate analysis, methyl-guanine-methyltransferase gene (MGMT) promoter methylation (p = 0.048), gross total tumour resection (p = 0.017), and calcium score (p = 0.011) were significant prognostic predictors in patients with GBM." (PMID 38592330, 2024). "Univariate analyses showed that age, tumor type, MGMT unmethylation, CD47, and high TIGIT expression were all associated with OS, whereas gender, tumor location, and pTERT mutations were unrelated to OS." (PMID 38404571, 2024). "We observed a higher level of MGMT expression in tumor tissues than paired normal tissues (p < 0.05)." (PMID 39041891, 2024). "This suggests that detecting MGMT methylation in sEV is more challenging in cases where the tumor has been previously removed." (PMID 38762534, 2024). "The influence of oncometabolites on this repair process was discovered because many of the brain tumor patients with a methylated MGMT promoter in tumor cells were IDH mutants, and they showed the best response to chemotherapy with alkylating agents." (PMID 39201738, 2024). "The repair process in tumor cells is carried out by the MGMT protein, so an unmethylated MGMT gene promoter, leading to high protein expression, is associated with resistance to TMZ treatment." (PMID 38762534, 2024). "The tumor was MGMT methylated, which usually means a better prognosis with temozolomide treatment, but ENM is related to poor prognosis." (PMID 39823071, 2024). "The proportion of tumours tested for IDH1 mutations and MGMT promoter methylation were high (97.9% and 92.3%, respectively)." (PMID 39767640, 2024). "MGMT-promoter methylation predicts a better response to the drug temozolomide (TMZ) compared to tumours with an unmethylated MGMT-promoter." (PMID 39256213, 2024). "There were no other significant associations between PMN-hit status and clinical variables such as age at diagnosis, telomere maintenance mechanism of the tumour, or MGMT promoter methylation status (respectively)." (PMID 38877600, 2024). "Patients with MGMT-unmethylated tumours have lower overall survival and less benefit from temozolomide compared to those with methylated tumours." (PMID 39099691, 2024). "In older patients, at least one retrospective study found that combined therapy had worse outcomes than radiation alone, and other studies found that the benefit of adding temozolomide decreased with age, particularly in those with MGMT unmethylated tumours." (PMID 39099691, 2024). "Lomeguatrib (O6-BTG), another MGMT inhibitor used in this study, not only efficiently inactivated the in vitro and in vivo MGMT level or activity in various tumors, but also effectively increased tumor sensitivity to TMZ26–29." (PMID 38811596, 2024).
tumor (continued). "When the MGMT gene is hypermethylated, its expression is silenced, rendering the tumor cells vulnerable to the effects of alkylating chemotherapy agents like temozolomide (TMZ)." (PMID 38203783, 2024). "In other studies, the MGMT methylation was seen predominately in the parietal and occipital lobes, temporal lobe or independent from tumour location." (PMID 39767640, 2024). "Despite a smaller effect (10 versus 7.9 months, HR 0.75, 95% CI 0.56–1.01), temozolomide improved survival in patients with MGMT unmethylated tumours (n = 189)." (PMID 39099691, 2024). "MGMT promoter methylation was detected in 19 (41.3%) of these patients using DNA of tumor tissue origin and in 14 (28%) patients using sEV-DNA." (PMID 38762534, 2024). "Patient data regarding the status of the tumour promoter O6-methylguanine-DNA methyltransferase (MGMT) were collected, and one of the seven patients was found to have an MGMT-methylated tumour." (PMID 38273249, 2024). "Compared with the model using only a single MRI sequence or the whole tumor region, the final radiomics model integrating multiple MRI sequences and multiple regions was found to be more accurate in identifying MGMT methylation." (PMID 38992201, 2024). "Increased expression and activity of the DNA repair protein O6-methylguanine-DNA methyltransferase (MGMT) is reported to be one of the most important mechanisms accounting for TMZ resistance of GBM tumor cells." (PMID 38675144, 2024). "The linkage of MGMT methylation status and MGMT protein expression has the potential to offer a more comprehensive picture of tumor biology, potentially leading to improved clinical outcomes and offering independent prognostic value." (PMID 38612892, 2024). "The average preoperative tumor volume was 18.1 cm3 (SD: 9.23, Range: 9.3–41.0), and 16.8% of tumors exhibited MGMT methylation status." (PMID 38893250, 2024). "In the case of elderly patients (>70 years old) who are not candidates for a combined-modality approach because of poor functional status or significant comorbidity, the MGMT methylation status of the tumour is useful for decision-making." (PMID 39099691, 2024). "At the voxel-wise level, no significant topological differences between MGMT-unmethylated and MGMT-methylated GBMs, as well as between highly and lowly MGMT-methylated tumours, were found." (PMID 39713243, 2024). "Methylation of the MGMT promoter can increase the killing effect of the alkylating agent chemotherapy drugs on tumour cells, reduce tumour cell proliferation and repair to prolong patients’ survival." (PMID 39594235, 2024). "However, this TMZ resistance may potentially be countered with poly(ADP-ribose) polymerase inhibitors (PARPi), inhibitors of the RecQ DNA helicase WRN, and newer chemotherapeutic agents specifically designed to induce DNA damage and death of MGMT-deficient tumor cells in an MMR-independent manner." (PMID 39012509, 2024). "The survival rate was 40 percent for patients with MGMT methylated tumours, while it was only 7 percent for patients with unmethylated tumours." (PMID 39099691, 2024). "MGMT, on the other hand, is an enzyme responsible for DNA repair, specifically by removing alkylating agents that can damage DNA and lead to tumor formation." (PMID 39767561, 2024). "Common practice includes a further course of TMZ in those patients with MGMT methylated tumours who relapse more than six months after completing adjuvant TMZ." (PMID 38225549, 2024). "One of the earliest mechanisms of resistance to TMZ is the upregulation of DNA methyltransferase (MGMT), which removes methyl adducts from DNA, enabling mismatch repair and allowing tumor DNA replication to continue." (PMID 39555054, 2024). "This epigenetic silencing of the MGMT gene increases the sensitivity of tumor cells to alkylating chemotherapeutic agents, leading to better treatment responses and potentially prolonged survival." (PMID 38203783, 2024).
tumor (continued). "Continued research at the molecular level has elucidated that the epigenetic modification of the MGMT gene, specifically the hypermethylation of its promoter region, is instrumental in augmenting the sensitivity of tumor cells to alkylating agents." (PMID 39055560, 2024). "The impact of tumor contact with neurogenic zones on clinical parameters, such as overall survival, multifocality, MGMT promotor methylation, Ki-67 and KPS score was also examined by multivariable regression analysis, chi-square test and Mann–Whitney-U." (PMID 38730694, 2024). "In 2017 a study that examined patient age, sex, race, MGMT methylation, performance status, resection extent, and tumor site used a Cox proportional hazard model to achieve a c-index of 0.695 ± 0.023 standard error for 1 year survival." (PMID 38798600, 2024). "This delivery approach successfully downregulated MGMT expression levels, resulting in increased chemotherapy sensitivity of tumor cells." (PMID 38254819, 2024). "The tumor MGMT methylation status is routinely obtained from surgical resection or biopsy in clinical practice." (PMID 38762534, 2024). "Gene silencing due to methylated MGMT results in a reduction of this antagonism and an increase in tumor sensitivity to chemotherapy." (PMID 38992201, 2024). "We analyzed the HK3 expression level in samples from TCGA stratified according to tumor grade, IDH mutation status and MGMT promoter methylation status." (PMID 37779195, 2023). "Localized application of pseudo-substrates or tumour-specific delivery of blocking peptides against MGMT increases TMZ efficiency." (PMID 37891744, 2023). "The MGMT promoter methylation (MGMT meth) of the tumour silenced its expression, making it impossible to repair the damage caused by alkylating agents, so the MGMT meth suggests that patients can benefit from temozolomide (TMZ) treatment." (PMID 36900232, 2023). "MGMT levels are higher in CSCs, and there have been reports of a correlation between the presence of CSCs in tumor tissue and the expression of MGMT." (PMID 37372456, 2023). "The study, whose primary endpoint is ORR at 3 months based on MGMT methylation on tumor tissue, has completed enrolment and results are being awaited." (PMID 36826067, 2023). "The MGMT promoter was methylated (≥10% of tumor cells) in 38% of primary tumors and 78% of recurrences, and this difference is statistically significant (Fisher exact test p-value = 0.03)." (PMID 36830847, 2023). "MGMT expression within cancer cells allows the cell to recover from the DNA damaging effects of alkylating agents enabling the tumour to become resistant to therapeutic use of such agents." (PMID 36198483, 2023). "We also identified that Ralo repressed MGMT and increased tumour cell sensitivity to TMZ by inhibiting PKN1." (PMID 37480215, 2023). "There seems to be a threshold: patients with low MGMT tumor levels (≤30 fmol/mg protein) responded better to TMZ than patients with MGMT activities above this level." (PMID 38068493, 2023). "The MGMT promoter methylation status was determined for all tumour and cell culture samples included in the study." (PMID 37620410, 2023). "In normal cells, the MGMT expression is regulated as a DNA repair mechanism, whereas, in tumor cells, the gene is silenced in certain profiles." (PMID 37937301, 2023). "Candidate gene-based studies have shown that hypermethylation of tumor suppressor genes, including p16, MGMT, RASSF1A, and APC, occurs early in neoplasia and rises with carcinoma development, implicating these processes in disease onset and progression." (PMID 38001653, 2023). "MGMT promoter unmethylated makes tumor cells less likely to benefit from DNA alkylation agents such as temozolomide or nitrosourea, and such patients have a shorter median survival." (PMID 37837543, 2023).
tumor (continued). "One notable mechanism involves the utilization of methylguanine (MGMT) to repair DNA damage, wherein the detoxification activity of MGMT helps tumor cells evade cell death induced by alkylating agents." (PMID 38202657, 2023). "MGMT methylation status was available in 11 patients, of whom 3 showed methylation in tumour biopsy samples (27%)." (PMID 36836456, 2023). "A series of other favorable prognostic factors have been reported previously, including MGMT methylation, tumor size, temporal tumor location, and younger age." (PMID 36756387, 2023). "In particular, the DNA repair protein, O6-methylguanine-DNA methyltransferase (MGMT), causes the resistance of tumor cells to alkylating agents, including TMZ." (PMID 37047356, 2023). "Despite not having a correlation with age (p = 0.684) or gender (p = 0.991, Logistic Regression), MGMT-methylated tumour patients had a lower PS at presentation (coef." (PMID 37373988, 2023). "When adjusting for major clinical confounding factors (age, ECOG PS, tumor location, extent of surgical resection, MGMT promoter methylation status), multivariable analysis confirmed the non-linear relationship between PFS and baseline fT3/fT4 (p = 0.01)." (PMID 37264256, 2023). "Bolstered by the clinical prediction that this MGMT-methylated tumor should respond well to TMZ, the patient underwent standard-of-care treatment with concurrent XRad and TMZ following subtotal resection." (PMID 37192626, 2023). "These factors represent different facets of the patient-disease-treatment matrix: age to patient physiology, morbidities, and tumor biology; MGMT to chemotherapy response; and GTV T1 to radiation dosage." (PMID 37637066, 2023). "During tumor development, methylation of the MGMT gene promoter can prevent DNA repair and increase the efficacy of alkylating agent chemotherapy." (PMID 37881322, 2023). "In terms of tumor grade, the 97 MGMT-positive cases included 71 NET-G1 cases, 21 NET-G2 cases, and 5 NET-G3 cases." (PMID 37161026, 2023). "In both cases, a hypermethylation of MGMT and ERCC-1 promoter was associated with decreased tumor regression." (PMID 36766755, 2023). "MGMT protein expression fluctuates, with tumor tissue expressing MGMT proteins at a lower level than normal tissue." (PMID 37901797, 2023). "The tumor was positive for MGMT methylation, and the patient remains in remission 19.5 months after treatment." (PMID 37554225, 2023). "Amongst 94 patients with good quality data to assess the MGMT promoter methylation status, 90 (95.7%) had a methylated tumor, and 4 (4.3%) an unmethylated tumor." (PMID 37665475, 2023). "More specifically, low MGMT expression, associated with methylation of the MGMT gene promoter, predicts responsiveness to TMZ, and the percentage of tumor cells that are actively proliferating (%Ki67+ cells) correlates with radiosensitivity." (PMID 37878712, 2023). "We believe that this targeted TNT-mediated communication and transfer of MGMT protects the tumor and surrounding cells from apoptosis induced by radiation and TMZ treatment." (PMID 37476291, 2023). "Approximately 39% and 13% of patients who harboured tumours with hypermethylated MGMT promoter survived 2 and 5 years, respectively, and confirms the prognostic and predictive value of methylation status." (PMID 36730349, 2023). "Such nanoparticles downregulate the expression of PD-L1 in tumor cells, thus reversing the tumor suppressive microenvironment and reducing the activity of MGMT." (PMID 37144620, 2023). "With this objective, methylation status of the MGMT promoter in histological tumor samples obtained from patients with LMS, dacarbazine-based regimens treated were measured and correlated with clinical outcomes." (PMID 37371106, 2023). "The treatment efficacy depends on the methylation status of the MGMT promoter in tumor tissue, meaning that only those with methylated promoters will significantly respond and have prolonged survival." (PMID 36766464, 2023).
tumor (continued). "The aim of this study was to investigate if there were correlations between the ADC values of the enhancing tumor and peritumoral areas of GBs and the MGMT methylation status." (PMID 36900177, 2023). "Determining MGMT methylation status is currently performed on the tumor when possible or on a biopsy." (PMID 37190181, 2023). "The risk scores were in agreement with previous clustering analyses and provided good discriminatory functions in terms of tumor molecular characteristics, such as fewer IDH1 mutations, 1p19q co-deletion, and MGMT methylation in the high-risk group." (PMID 37403043, 2023). "Patients with advanced, gastro-entero-pancreatic or lung well-differentiated NETs candidate to TEM-based chemotherapy and with available tumor samples for MGMT-promoter methylation assessment were included." (PMID 36826067, 2023). "A higher percentage of MGMT promoter methylation was related to lower preoperative tumour volume (p = 0.003), a lower likelihood of 5-ALA positive fluorescence (p = 0.041) and a larger extent of resection EoR (p = 0.041)." (PMID 37373988, 2023). "Despite showing MGMT promoter hypermethylation by MS-PCR, MGMT protein was detected in cytokeratin-positive tumor cells from six of the nine baseline biopsy samples." (PMID 37387791, 2023). "MGMT expression by qRT-PCR was performed on tumours from 25 patients from whom FF tissue was available." (PMID 36198483, 2023). "A methylated MGMT promoter in tumor cells was found in 8 patients, whereas 5 patients had an unmethylated MGMT promoter (cut off 10%)." (PMID 37345035, 2023). "A minimum of 70% tumor cellularity is preferred for MGMT promoter analysis, a cutoff also recommended in other diagnostic assays such as methylation profiling arrays." (PMID 37919784, 2023). "In 5 cases MGMT was unmethylated in the parental tumour, whereas it was found methylated in the derived cell culture (UM→M, 8%)." (PMID 37620410, 2023). "Improved outcomes from these immunotherapies were mainly observed in patients with methylated MGMT promoter tumours." (PMID 38136335, 2023). "Similar diagnostic challenges exist for the detection and categorization of the MGMT promoter methylation status in tumor tissue." (PMID 36831536, 2023). "This includes the extent of resection (EOR), O6-methylguanine DNA methyltransferase (MGMT) promoter methylation status, patient age at time of diagnosis, tumor location, or occurrence of neurological deficits." (PMID 37568723, 2023). "The standard-of-care molecular analysis reported that MGMT promotor methylation status was available for 78/81 (96.3%) fluorescent tumours." (PMID 36983696, 2023). "The traditional method to determine MGMT methylation status involves the extraction of tumor tissue through surgery." (PMID 36841898, 2023). "The tumour sample in PanSPS_044 (III-1) showed loss of expression for MLH1/PMS2 and was BRAF mutated and MGMT methylated." (PMID 36270769, 2023). "In this study, we examined 146 Pan-NENs cases including 19 STZ-treated cases by IHC staining and reported the MGMT expression profile by tumor grade in Pan-NET." (PMID 37161026, 2023). "Age, BMI, RPA, MGMT status, cortical vs. periventricular location, tumor location, and the administration of VPA were statistically significant for PFS." (PMID 37892181, 2023). "We found that of the 12 patients with LMD relapse whose MGMT promoter methylation status was known, all had unmethylated tumours." (PMID 37715122, 2023). "The results showed that a low PANoptotic score was associated with high tumor purity, while samples with 1p19q co-deletion, IDH mutation, and MGMT promoter methylation have lower PANoptotic scores compared to wild-type samples." (PMID 37501725, 2023).